DNMT1 (DNA methyltransferase 1)
Diseases named in the same sentence as DNMT1 in open-access papers (continued):
Sharing a sentence is not in itself a finding about the gene and the disease.
ovarian carcinoma (continued). "Epigenetic regulation through the inhibition of DNMT1 as a mechanism to alter stemness traits is a finding that is not yet reported for ovarian cancer cells." (PMID 37189618, 2023). "DNMT1 is a direct target of miR-30a-5p and miR-30c-5p, and the overexpression of miR-30a-5p and miR-30c-5p-inhibited DNMT1 promoted cisplatin sensitivity and partially reversed EMT in ovarian cancer cell lines." (PMID 36984544, 2023). "Interestingly, this group found that miR30a/c-5p directly targets DNMT1 3′UTR, inhibiting its expression and directing a feedback loop that uncovers additional mechanisms in ovarian cancer drug resistance." (PMID 37239435, 2023). "We found higher expression of DNMT1 (p = 0.0325), DNMT3A (p = 0.0394), DNMT3B1 (p = 0.0068), DNMT3B3 (p = 0.0171), DNMT3B5 (p = 0.0039), DNMT3B6 (p = 0.0143), and DNMT3B3Δ5 (p = 0.0148) in high-grade ovarian carcinoma." (PMID 36361550, 2022). "As the authors of this study claim, miR-30a/c-5p is aberrantly methylated and thus silenced by overexpressed DNMT1, which relieves the inhibitory effect of miR-30a/c-5p on DNMT1 and Snail (a key inducer of EMT), leading to cisplatin resistance and partial EMT in ovarian cancer in vitro." (PMID 34298969, 2021). "In summary, we obtained novel evidence showing that low expression levels of ALDH1A2 are correlated with an early tumor stage and poor prognosis for ovarian cancer patients, and that its expression is negatively regulated by the methylation of ALDH1A2 via DNMT1 or DNMT3B." (PMID 31615043, 2019). "Furthermore, the ALDH1A2 gene was found to be hypermethylated via DNMT1 or DNMT3B in ovarian cancer cell lines, indicating that ALDH1A2 expression is regulated by epigenetic regulation via DNMT." (PMID 31615043, 2019). "Yet in our study, we found that DNMT1 knockdown alone induced CHFR promoter hypomethylation significantly in A2780 and 3AO cells, which, in turn, led to increased expression of CHFR mRNA and protein in ovarian cancer cell lines." (PMID 29367628, 2018). "In summary, we observed for the first time that STON2 acts as a negative modulator in ovarian cancer cells via DNMT1/MUC1-mediated epigenetic mechanisms." (PMID 30518424, 2018). "Since DNMT1 is one of the DNA methyltransferases, we knocked down DNMT1 by specific siRNAs and observed whether genetic reduction of DNMT1 altered the methylation of the CHFR promoter and the expression of CHFR in ovarian cancer cells." (PMID 29367628, 2018). "Recent reports suggest DNMT1 and HDAC1 expression increases with ovarian cancer stage." (PMID 24475290, 2014). "Our study supports RGS10 genes as targets for demethylating and acetylating therapy and identifies RGS10 de-suppression as a likely contributing mechanism for the clinical efficacy of DNMT1 and HDAC1 inhibitors in the treatment of chemoresistant ovarian cancer." (PMID 24475290, 2014). "Haplotype analysis of DNMT1, DNMT3B, and DNMT3A polymorphisms did not reveal SNP combinations associated with the risk of ovarian cancer development." (PMID 23666104, 2013). "The results indicated that the mRNA expression of DNMT1, DNMT3b and class I HDACs was increased in ovarian cancers, while the expression of DNMT3a was not different between cancer tissues and normal ovaries." (PMID 23420051, 2013). "Therefore, we evaluated the possible association of single nucleotide polymorphisms (SNPs) of DNA methyltransferases (DNMTs) genes, including DNMT1, DNMT3B, and DNMT3A, with ovarian cancer development in the Polish population." (PMID 23666104, 2013). "Furthermore, the expression of DNMT1, DNMT3b, HDAC1 and HDAC2 was significantly higher in stage III/IV compared with stage I/II ovarian carcinomas." (PMID 23420051, 2013). "The expression of DNMT1 and DNMT3b was assessed in situ on paraffin sections of normal ovarian tissues (n=8) and malignant ovarian tumors (n=22)." (PMID 23420051, 2013).
ovarian carcinoma (continued). "Therefore, to maintain RGS2 repression during ovarian cancer progression, RGS2 promoter might require the accumulation of DNMT1." (PMID 37649067, 2023). "However, the combination of the DNMT1 inhibitor, Azacytidine, with an irreversible inhibitor of polyamine biosynthesis, α-di-fluoromethylornithine, increased M1 macrophages in the TME of an ovarian cancer model." (PMID 33859645, 2021). "Further investigation demonstrated the contribution of HDAC1 and DNMT1 to silencing of RGS10 during acquired chemo-resistance and revealed the importance of HDAC1 and DNMT1 inhibition as an assistant therapeutic approach to overcome ovarian cancer chemo-resistance." (PMID 33680048, 2020). "Thus, our findings suggest that paclitaxel induces UBC13 down-regulation, which facilitates cell resistance to paclitaxel, and a pathway consisting of DNMT1, CHFR, and Aurora A probably participates in UBC13 regulation of the sensitivity to paclitaxel in ovarian cancer cells." (PMID 29367628, 2018). "In addition, both 5Aza treatment and DNMT1 and DNMT3A knockdown increased TIMP2 mRNA and protein expression and reduced DNA methylation of the TIMP2 promoter, suggesting that TIMP2 expression is down-regulated by DNA methylation in ovarian cancer cells." (PMID 28620234, 2017). "Using PCR–RFLP and HRM analyses, we studied the prevalence of the DNMT1 rs8101626, rs2228611 and rs759920, DNMT3A rs2289195, 7590760, rs13401241, rs749131 and rs1550117, and DNMT3B rs1569686, rs2424913 and rs2424932 SNPs in patients with ovarian cancer (n = 159) and controls (n = 180)." (PMID 23666104, 2013). "However, none of the other nine studied DNMT1, DNMT3B and DNMT3A SNPs exhibited significant association either in dominant or recessive inheritance models with ovarian cancer development." (PMID 23666104, 2013). "Furthermore, haplotype and multifactor dimensionality reduction analysis of the studied DNMT1, DNMT3B, and DNMT3A polymorphisms did not reveal either SNP combinations or gene interactions to be associated with the risk of ovarian cancer development." (PMID 23666104, 2013). "One of the first studies of DNMT expression in ovarian tumors used cancer cell lines and showed an increased expression of DNMT1 and DNMT3B, but not DNMT3A mRNA levels, in ovarian cancer cell lines compared to normal ovarian surface epithelial cells." (PMID 37894317, 2023). "siRNA silencing of DNMT1 or DNMT3B restored the expression of ALDH1A2 and reduced methylation in ovarian cancer cells, whereas no significant changes in ALDH1A2 expression were observed upon knockdown of DNMT3A." (PMID 31615043, 2019). "Furthermore, down-regulated CHFR inhibited paclitaxel sensitivity, elevated Aurora A expression, but did not affect DNMT1 and UBC13 in ovarian cancer cells, and vice versa." (PMID 29367628, 2018).
gastric cancer (110 papers, 2007 to 2025). A primary or metastatic malignant neoplasm involving the stomach. "In particular, in gastric cancers, the overexpression of DNMT1 correlated with poor tumor differentiation and caused the hypermethylation of multiple CpG islands, including those of p16, hMLH1, and E-cadherin." (PMID 36979633, 2023). "Firstly, DNMT1 overexpression was shown to methylate and silence the GSN gene, and secondly, DNMT1 overexpression was associated with higher TAMs infiltration in the TME of gastric cancer." (PMID 33535484, 2021). "It was reported that the activity of DNMT1 was increased in EBV-associated gastric cancer and in NPC cell lines, LMP1 up-regulates the expression of these three DNMTs." (PMID 30615685, 2019). "A previous study, in a gastric cancer cell line, showed that quercetin and isoliquiritigenin decreased DNMT1 and DNMT3a protein levels, causing slight demethylation of the promoter region of the BCL7A gene." (PMID 30409182, 2018). "Through TCGA database, DNMT1 overexpression increased gastric cancer risk, but unrelated with clinicopathological parameters and prognosis." (PMID 29221215, 2017). "In the present study, we explored the associations of five SNPs of DNMT1 gene (rs16999593, rs10420321, rs2288349, rs2228611, and rs2228612) with postoperational survival in Chinese gastric cancer patients." (PMID 27087738, 2016). "The association between the SNPs of the DNMT1 gene with H. pylori infection, gastric atrophy and gastric cancer in the Chinese Han population were studied." (PMID 23049933, 2012). "We investigated the associations between SNPs in the DNMT1 gene and risks of developing H. pylori seropositivity, gastric atrophy and gastric cancer in the Chinese population." (PMID 23049933, 2012). "Additionally, tumor-associated macrophages increase DNMT1 expression in gastric cancer cells, leading to the silencing of the tumor-suppressing gelsolin gene." (PMID 38988323, 2024). "Meta-analysis of the association of DNMT1 (rs16999593) polymorphism with risk of gastric cancer." (PMID 37878642, 2023). "Furthermore, lower expression of DNA methyltransferase 1 is associated with increased expression of GSN in gastric cancer cell lines (AGS)." (PMID 36291171, 2022). "The AKT-NFκB and STAT3 signaling pathways can upregulate DNMT1 expression, which could cause aberrant DNA methylation of tumor suppressor genes and lead to gastric cancer." (PMID 28473984, 2017). "In summary, our study provides the first evidence that polymorphisms of the DNMT1 gene could modify the postoperational survival of gastric cancer cases." (PMID 27087738, 2016). "Therefore, SNP rs16999593 (T/C), which causes a histidine to arginine substitution at 97 positions of the amino acid sequence, might affect the function of DNMT1, thus increasing susceptibility to gastric cancer." (PMID 28473984, 2017). "However, the mechanisms underlying the aberrant expression of miR-148a and DNMT1, and their association in gastric cancer remain unknown." (PMID 25351138, 2015). "It has been reported that DNMT1-mediated epigenetic silencing of miR-200b/a/429 facilitates the development of gastric cancer and glioblastoma." (PMID 38890707, 2024). "Previous studies have shown elevated levels of DNMT-1- and DNMTs-3A/3B-protein expression in both HP-induced gastritis and gastric carcinomas." (PMID 38542354, 2024). "Our study indicates that SNHG3 regulates SEPT9 methylation by targeting miR-448/DNMT1 and subsequently affecting the occurrence and development of gastric cancer." (PMID 35528235, 2022).
gastric cancer (continued). "The results showed that along with increasing patients' age, the DNMT1 gene expression will increase in gastric antral epithelial cells of gastric cancer patients (P ≤ 0.05)." (PMID 36147796, 2022). "Suppression of DNMT1 by miR-148-3p has been reported in pancreatic, liver, bladder, oesophageal and gastric cancers." (PMID 35022525, 2022). "LncRNA HOXA11-AS promotes the proliferation and invasion of gastric cancer through the chromatin modification factors, which including polycomb repressive complex 2 and Dnmt1." (PMID 34215719, 2021). "LMP2A up-regulates the expression of DNMT1 and DNMT3B in EBV-associated gastric carcinoma (latency I)." (PMID 32841292, 2020). "For instance, LMP2A was found to induce the phosphorylation of STAT3 that activates DNMT1 transcription and leads to the loss of PTEN expression, a common phenomenon observed in EBV-associated gastric carcinoma." (PMID 32748879, 2020). "LMP2A also increased the methylation of PTEN in gastric cancer cell lines by inducing DNMT1 expression." (PMID 30615685, 2019). "This study identifies the gastric cancer-associated genes such as EGFR, KLF4, DNMT1 and AGO4 as candidates of ceRNA network in gastric cancer." (PMID 29719612, 2018). "miR-148a modulates the expression of runt-related transcription factor 3 (RUNX3), an important tumor suppressor, through inhibition of DNMT1-dependent DNA methylation in gastric cancer." (PMID 29721215, 2018). "In summary, our study results showed differentially regulated lncRNAs and gastric cancer-associated genes such as EGFR, KLF4, DNMT1 and AGO4 are candidates of ceRNA network in gastric cancer." (PMID 29719612, 2018). "Extensive evidence has suggested that DNA methylation is involved in the initiation and progression of gastric cancer and increased expression of DNMT1 had been confirmed to be related to gastric cancer." (PMID 28473984, 2017). "In 65 gastric cancer tissues, DNMT1 expression was significantly increased, whereas Hace1 expression was significantly reduced." (PMID 28584243, 2017). "In the meta and bioinformatic analysis, we found that DNMT1 expression was higher in gastric cancer, compared with normal (p < 0.00001), para-cancerous (p = 0.0004) and dysplasia (p < 0.00001) tissues." (PMID 29221215, 2017). "One early study observed that viral latent membrane protein 2A (LMP2A) increased DNMT1 expression, and that knockdown of STAT3 by siRNA counteracted LMP2A-mediated DNMT1 expression in gastric carcinoma cells." (PMID 28360411, 2017). "Studies have shown that miR-148a is downregulated and DNMT1 is overexpressed in gastric cancer cells." (PMID 25351138, 2015). "In gastric cancer, it has been demonstrated that E-cadherin gene (CDH1) hypermethylation is associated with DNMT1 overexpression by EBV infection." (PMID 26032781, 2015). "In gastric cancer, it has been demonstrated that hypermethylation of CDH1, which expresses the E-cadherin protein, is associated with DNMT1 overexpression by EBV infection." (PMID 26032781, 2015). "Gastric cancer cells are often characterized by overexpression of Dnmt1 with hypermethylation of genes relevant to the etiology of gastric cancer, including human MutL homologue 1 (hMLH1), thrombospondin-1 (THBS-1), and E-cadherin." (PMID 17805414, 2007). "It has been reported that EZH2 depletion mediates histone H3K27 trimethylation and reduces the enrichment of DNMT1 on the miR-200b/a/429 promoter, thus abolishing transcriptional silencing of miRNAs and suppressing tumor growth in gastric cancer and glioblastoma." (PMID 38890707, 2024). "Moreover, DNMT1 expression in gastric carcinomas and solid tumors has been shown to be significantly associated with chemotherapy response." (PMID 37147733, 2023).
gastric cancer (continued). "LncRNA SNHG1 elevated the expression of DNMT1, which promoted gastric cancer cell proliferation." (PMID 35678255, 2022). "At the same time, circ-RanGAP1/miR-877-3p may have 10 binding sites, such as DNMT1 in gastric cancer." (PMID 34249673, 2021). "Furthermore, the overexpression of DNMT1 protein in gastric cancer tissues is significantly related to decreased E-cadherin expression, which indicates that an increase in DNMT1 expression will enhance the migration ability of the cancer cells." (PMID 32751889, 2020). "In addition, TAMs promote the epigenetic silencing of gelsolin through DNA methyltransferase 1 activity induced by CCL5/CCR5/STAT3 signaling in gastric cancer cells." (PMID 31892854, 2020). "Similarly, HOXA11-AS is able to recruit EZH2 via the DNMT1 methyltransferase complex to regulate miR-1297 and promote gastric cancer cell proliferation and invasion." (PMID 31757938, 2019). "In addition to the lncRNAs, we also profiled the expression pattern of identified candidate gastric cancer-associated genes EGFR, FGFR2, KLF4, DNMT1 and AGO4 shortlisted from the analysis of genes by relative quantification." (PMID 29719612, 2018). "The suppression of miR-148a may contribute to the down-regulation of MEG3 in gastric cancer by modulating the activity of DNMT1." (PMID 29069869, 2017). "The aim of our study was to explore the role of SNPs of DNMT1 in the prognosis of gastric cancer." (PMID 27087738, 2016). "Polymorphisms of DNMT1 may modify the role of DNMT1 in prognosis of gastric cancer (GC)." (PMID 27087738, 2016). "DNMT1 was also involved in gastric carcinomas treated by neoadjuvant chemotherapy." (PMID 25927928, 2015). "Silencing of miR-148a reduces its suppression of DNMT1 in gastric cancer, and this might result in overexpression of DNMT1, promoting DNA hypermethylation." (PMID 23683438, 2013). "Several studies have found that DNMT1 is over-expressed in human cancers including gastric cancer, suggesting that it may be involved in tumorgenesis and tumor progression." (PMID 23049933, 2012). "Over-expression of DNMT1 mRNA and protein is detected in gastric cancer suggesting that DNMT1 may contribute to tumorgenesis." (PMID 23049933, 2012). "A potential mediator is DNA methyltransferase 1 (DNMT1) that is upregulated in naturally infected gastric cancers and could help establish methylation patterns propagated to daughter cells upon cell division." (PMID 21194482, 2010). "Similarly, SNHG1 has been shown as a contributor to gastric cancer proliferation through DNMT1." (PMID 34712495, 2021). "Mediated methylation by DNMT1 and EZH2 has been reported to silence the miRNA-200 gene and promote the progression of gastric cancer and glioblastoma." (PMID 38988323, 2024). "In gastric cancer, one study showed the contribution of the epigenetic factors of the DNA methyltransferase (DNMT) family (DNMT1, PRMT, and KDM6B), which led to the upregulation of M2 and TAMs within TAMs." (PMID 37111629, 2023). "Tumor-associated macrophages (TAMs) were co-cultured with gastric cancer cells, and DNA methyltransferase 1 (DNMT1) expression increased; however, GSN expression decreased in gastric cancer cells." (PMID 37035750, 2023). "Knockdown of lncRNA SNHG3 upregulates miR-448 and suppresses DNMT1 expression, thereby inhibiting DNMT1-mediated SEP9 methylation and upregulating SEP9 expression to suppress gastric cancer progression." (PMID 35528235, 2022). "Quantitative real-time PCR (qRT–PCR) was used to detect SNHG3 and miR-448 in gastric cancer, and a dual-luciferase experiment verified the effects of SNHG3, miR-448, and DNMT1." (PMID 35528235, 2022).